BDNF (brain derived neurotrophic factor)
Diseases named in the same sentence as BDNF in open-access papers (continued):
Sharing a sentence is not in itself a finding about the gene and the disease.
depression (continued). "In this study, we report that Xiangshao granule also exerts antidepression activity by increasing the expression of hippocampal BDNF and TrkB expression in a depression mouse model." (PMID 24367385, 2013). "Based on these studies, our findings suggest that pups born to dams exposed to supra-therapeutic dose of buprenorphine show depression-like characteristics with decreased level of BDNF and serotonin." (PMID 24367510, 2013). "BDNF is implicated in synaptic plasticity, and proteins as neuritin that are induced by BDNF are decreased in stress-induced animal models of depression and increased after chronic antidepressant treatment, contributing to the BDNF antidepressant effect." (PMID 23862076, 2013). "In this regard, particular attention has been afforded the involvement of diminished brain-derived neurotrophic factor (BDNF) in depression as this growth factor ordinarily enhances neurogenesis and promotes neuronal cell survival and neurite growth." (PMID 24019878, 2013). "In summary, we characterized the roles of BDNF and its related miRNAs in the pathogenesis of depression and validated that miR-182 was a novel miRNA that regulated the BDNF levels." (PMID 23704927, 2013). "Hippocampal BDNF levels in post-mortem brains of depression patients were found to be higher in those treated with antidepressants at time of death." (PMID 23847583, 2013). "In support of an antidepressant role of BDNF, serum levels of BDNF have been found to be decreased in patients with major depression." (PMID 24244357, 2013). "BDNF triggers TrkB receptor-dependent different intracellular signaling pathways and exhibits beneficial effect for the treatment of depression in experimental studies." (PMID 24367385, 2013). "Initial preclinical studies showing that expression of BDNF was downregulated in the dentate gyrus and hippocampus of rats subjected to chronic stress have attracted interest of researchers on the potential involvement of BDNF in depression." (PMID 24222865, 2013). "Together, these data encourage further investigation into the role of the dorsal striatum in depression and anxiety, and the apparent differences that arise from whole brain and region-specific manipulation of BDNF or TrkB." (PMID 24369067, 2013). "Depressed patients show decreased levels of serum BDNF, which is correlated with decreased hippocampal volume and increased ratings of depression." (PMID 23691371, 2013). "Here this study was aimed to identify and characterize the roles of BDNF and its putative regulatory miRNAs in depression." (PMID 23704927, 2013). "A large body of evidence for the important role of the changes in theneurotrophin level, BDNF especially, in depression pathogenesis has beenaccumulated over the past decades." (PMID 24455189, 2013). "Several studies have shown the involvement of BDNF in the pathogenesis of neurodegenerative diseases and psychiatric disorders, like depression and schizophrenia." (PMID 24300402, 2013). "At this time there is insufficient information available to firmly conclude that pro-inflammatory cytokines promote depression through their actions on BDNF or other growth factors." (PMID 23675319, 2013). "Our results showed a significant negative correlation (Spearman rs = −0.307, P = 0.006) between the serum BDNF levels and the miR-132 levels in patients with depression (n = 40) and controls (n = 40)." (PMID 23704927, 2013). "Mice treated with fluoxetine in an enriched condition improved their depression-like phenotype compared to controls, displaying higher saccharin preference, higher brain BDNF levels and reduced corticosterone levels." (PMID 23653679, 2013). "The data regarding NGF involvement in depression have been more sparse than those involving BDNF and FGF-2." (PMID 23675319, 2013).
depression (continued). "Despite the suggestion of a role for epigenetic modulation of BDNF activity in depression and suicide, only one study has demonstrated a modest association between increased methylation of one BDNF CpG site with current PTSD status." (PMID 23847551, 2013). "Rodent models of chronic stress and depression have recapitulated these region-specific changes of BDNF." (PMID 24409146, 2013). "It is possible that cytokine and/or BDNF contribute to particular symptoms of depression, or particular depressive subtypes." (PMID 23675319, 2013). "Lower levels of BDNF in depression patients suggest a role of BDNF in the pathogenesis of depression." (PMID 23847583, 2013). "In type 2 diabetes subjects, BDNF serum levels were significant correlations with genotypes (r = −0.346, p < 0.01), depression scores (r = −0.486, p < 0.01) and HbA1c (r = −0.168, p < 0.05)." (PMID 23968401, 2013). "Significant differences in plasma BDNF levels have been observed for patients with depression who were assigned to the Mediterranean diet compared with those assigned to a control diet." (PMID 23286788, 2013). "We have identified that the serum BDNF levels were decreased and the BDNF-related miRNAs including miR-182 and miR-132 were increased in human subjects with depression compared with control subjects." (PMID 23704927, 2013). "Accumulating evidence suggests that impaired BDNF signaling or disturbed serotonergic neurotransmission is the key mechanism in the pathophysiology of depression." (PMID 24367510, 2013). "Serum CRH, CORT, and ACTH levels were significantly increased in depression mice compared with control (P < 0.05) and the expression levels of hippocampal BDNF and TrkB were reduced in the model group (P < 0.05)." (PMID 24367385, 2013). "A diet rich in omega-3 fatty acids, which has been shown to have positive effects on depression, also increases BDNF levels in the hippocampus." (PMID 23847583, 2013). "The depression-like phenotypes in pups were accompanied by elevation of oxidative stress, reduction of plasma levels of BDNF and serotonin, and attenuation of CREB signaling." (PMID 24367510, 2013). "Emerging evidence shows that brain-derived neurotrophic factor (BDNF) and microRNAs (miRNAs) play critical roles in the etiology of depression." (PMID 23704927, 2013). "Genetic variations of neurotrophic factors, such as brain-derived neurotrophic factor (BDNF), and transforming-growth-factor-β1 (TGF-β1) are known to increase the risk to develop LOAD and have also been related to depression susceptibility in LOAD." (PMID 24082824, 2013). "Moreover, TG2 may be a factor in the serotonin deficiency associated with major depressive disorder: increased levels of TG2 probably convert serotonin to Rac1, resulting in decreased levels of serotonin and BDNF that are associated with major depressive disorder." (PMID 23503168, 2013). "The link between HPA-axis, depression, and BDNF has been explored in rodent models of depression and given much attention." (PMID 23847583, 2013). "Increasing attention has been devoted to the possibility that growth factors, such as brain derived neurotrophic factor (BDNF), through actions on neurogenesis and neuroplasticity, contribute to the evolution of depressive disorders." (PMID 23824678, 2013). "Another candidate gene for depressive disorders is the Brain Derived Neurotrophic Factor (BDNF), which has previously been shown to act in synergy with serotonin." (PMID 23518193, 2013). "This also warrants further research on the exact contribution of BDNF in the pathophysiology of depression and its antidepressant action." (PMID 22581450, 2012). "Numerous studies have demonstrated that BDNF is involved in the onset and development of depression." (PMID 23056528, 2012).
depression (continued). "Evidence from animal experiments and postmortem studies has consistently suggested that reduced BDNF level in the hippocampus is responsible for decreased proliferation of hippocampal neurons and consequent onset of depression." (PMID 23056528, 2012). "This assumption is supported by findings that the antidepressant effects of medications used in chronic-stress models of depression are mediated by an increase in BDNF levels in the hippocampus." (PMID 23584115, 2012). "Studies also indicated that the decreased BDNF level was observed in chronic pain, depression, epilepsy, and neurodegenerative diseases such as Alzheimer's disease, PD, and Huntington's disease." (PMID 23304227, 2012). "Brain-derived neurotrophic factor, another neurotrophic factor, has also been shown to be effective in treating depression and Alzheimer's disease." (PMID 23300823, 2012). "For instance, an etiological link between the development of depression and BDNF has been suggested." (PMID 22606285, 2012). "In a study of a Japanese sample of depressed patients and non-depressed controls recruited from four academic medical centers, Fuchikami and colleagues assessed the relation between BDNF promoter methylation in white blood cells and depression." (PMID 22738307, 2012). "Meta-analyses have identified serum levels of brain-derived neurotrophic factor (BDNF) as a potential biomarker for major depressive disorder (MDD)." (PMID 22880079, 2012). "Support for a role of BDNF produced by astrocytes in the pathophysiology of depression comes from in vivo experiments using conditional BDNF knockout mice with a selective BDNF gene deletion in the forebrain." (PMID 22581450, 2012). "Although the role of BDNF in depressive behavior is yet to be clearly understood, a potential role of genetic variation in BDNF and antidepressant treatment outcome in depression has been reported." (PMID 22606285, 2012). "Antidepressants increase hippocampal neurogenesis, which action is followed by decreased depression and anxiety, via a GR-dependent mechanism involving GR phosphorylation and activation of a specific set of genes including BDNF gene." (PMID 21799699, 2012). "Do BDNF related symptoms (depression mood, anhedonia and suicide) appear based on this potential mechanism?" (PMID 23071556, 2012). "In particular, decreases in BDNF levels have been reported in animal models of depression and BDNF administration has been shown to produce antidepressant effects." (PMID 22768299, 2012). "Antidepressant-induced BDNF protein functions importantly to increase neurogenesis to ameliorate the symptoms of depression." (PMID 21799699, 2012). "There is strong evidence from the literature indicating that depression reduces serum BDNF concentrations in humans." (PMID 23245944, 2012). "Female BDNF knockouts displayed deficits on a forced swim task considered to be a measure of depression and deficit sucrose preference, a measure of anhedonia." (PMID 22912626, 2012). "Postmortem studies of individuals who have died from suicide also report that cortical levels of BDNF closely correspond to serum levels in individuals diagnosed with depression." (PMID 23304508, 2012). "Brain-derived neurotrophic factor (BDNF) is involved in major depressive disorder and neurodegenerative diseases." (PMID 21247257, 2012). "Postmortem analyses of brain tissues from patients with major depression showed a reduction in brain BDNF and in serum BDNF, whereas brain infusion of BDNF produced anti-depressant-like action in animals." (PMID 22973399, 2012). "The role of BDNF and neurogenesis in depression has also been a focus of attention in the animal literature on depression." (PMID 22912626, 2012). "Earlier findings show seasonality in processes and behaviors such as brain plasticity and depression that in part are regulated by Brain-Derived Neurotrophic Factor (BDNF)." (PMID 23133609, 2012).
depression (continued). "Based on this we investigated seasonal variation in serum BDNF concentrations in 2,851 persons who took part in the Netherlands Study of Depression and Anxiety (NESDA)." (PMID 23133609, 2012). "In 2002, the involvement of serum BDNF in stress and major depression was reported for the first time." (PMID 22761741, 2012). "We verified the role of hippocampal miR-16 and BDNF expression in early life stressor-induced depression-like behaviors." (PMID 23056528, 2012). "BDNF regulates the development and plasticity of neural circuits involved in mood disorders such as depression." (PMID 22768299, 2012). "Patients in the remission group had significantly higher plasma BDNF levels at remission than in the depressive syndrome and response stages (repeated-measures ANOVA; F1, 37 = 25.083, p<0.001)." (PMID 22761741, 2012). "Plasma BDNF levels in the depressive syndrome, response and remission stages in the remission group were 1 827±1 340, 2 402±1 610, and 3 158±2 033 pg/ml, respectively." (PMID 22761741, 2012). "Cytokines have equally recently received much attention in depression field also in relation with BDNF." (PMID 22654714, 2011). "It is well known that the stress-induced decreases in BDNF and antidepressant-stimulated increases in BDNF play important roles in the pathophysiology and therapeutic mechanisms of depression, respectively." (PMID 21912609, 2011). "This seems particularly true for BDNF in the case of AD, which co-prevalence with major depression is high." (PMID 22654714, 2011). "CREB also target other genes, such as brain-derived neurotrophic factor (BDNF), that is significantly involved in depression, serving as potential marker for treatment together with P-CREB." (PMID 21626018, 2011). "BDNF levels have been reported to be reduced in patients with depression, and antidepressants seem to up-regulate BDNF and other neurotrophic and growth factors." (PMID 21298116, 2011). "In fact, BDNF plasma levels were found to be significantly increased during exercise in non medicated patients with moderate depression." (PMID 22654714, 2011). "Proinflammatory response induces decreased neurogenesis in depression, which is characterized by decreased brain-derived neurotrophic factor (BDNF), neural cell adhesion molecule (NCAM) and fibroblast growth factor (FGF)." (PMID 21350721, 2011). "Another line of evidence supporting a role of BDNF in depression is the trophic effect of BDNF on the serotoninergic system." (PMID 22654714, 2011). "Aberrant activity of the dopaminergic- and BDNF systems have been implicated in the psychopathology of psychiatric disorders such as post-traumatic stress disorder (PTSD) and depression, as well as drug abuse." (PMID 22022509, 2011). "Hypothalamic-pituitary-adrenal (HPA) axis dysregulation and reduced neuroplasticity in depression are consistent with the assumption that BDNF is a stress-responsive intercellular messenger modifying HPA axis activity." (PMID 22194899, 2011). "Reductions in serum BDNF levels have been reported in patients with depressive disorders, whereas increased BDNF levels are seen following antidepressant treatment." (PMID 22654716, 2011). "We examined the methylation profile of 2 CpG islands (I and IV) at the promoters of the brain-derived neurotrophic factor (BDNF) gene, which is well known to be involved in the pathophysiology of depression." (PMID 21912609, 2011). "Environmental stressors induce depression and decrease BDNF mRNA, whereas antidepressants increase BDNF mRNA in the brain via 5-HT2A and β-adrenoreceptor subtypes." (PMID 20405001, 2010). "They do not add directly to the evidence linking adult neurogenesis with depression, but strengthen understanding of the role of BDNF and its receptor in the action of anti-depressants such as fluoxetine." (PMID 21048974, 2010).
depression (continued). "For example, while the antidepressant efficacy is suppressed in experiments using inducible BDNF knock-out mice, depression-related behaviors are only seen in females, showing significant gender differences." (PMID 20219105, 2010). "In regard to depression, it is well known that exogenous delivery of neurotrophic factors, such as BDNF and/or neurotrophin 3 (NT-3) promotes the function, sprouting, and regrowth of 5-HT neurons in the rat brain." (PMID 20405001, 2010). "BDNF and TrkB have been shown to regulate development of depression-like phenotypes and anxiety-related behaviors, depicting TrkB as a promising target for the development of new therapeutic compounds." (PMID 20333308, 2010). "In our study, real-time PCR experiments revealed a marked decrease in BDNF expression in hippocampus of mice submitted to our protocol of depression, when assessed at both the 6- and the 24-h time-points (an approximate 50% reduction)." (PMID 21194425, 2010). "It has been well-documented that antidepressants present the potential to upregulate the expression of brain-derived neurotrophic factor (BDNF) in animal models as well as the patients with depression." (PMID 20559500, 2010). "In various animal models of depression, the BDNF level is decreased, whereas chronic antidepressant medication and electro-convulsive shocks increase the levels in the hippocampus." (PMID 20219105, 2010). "Alterations in brain-derived neurotrophic factor (BDNF) gene expression contribute to serious pathologies such as depression, epilepsy, cancer, Alzheimer's, Huntington and Parkinson's disease." (PMID 19737418, 2009). "Following earlier findings both in animal and human studies, and the connections between BDNF and serotonin in depression, we measured basal levels of BDNF in two major brain regions in the hippocampus: DG and CA3." (PMID 21152205, 2009). "BDNF supports survival and differentiation of embryonic neurons and controls various neural processes in adulthood, including memory and learning, depression, and drug addiction." (PMID 19737418, 2009). "Proclaimed as the ‘dynamic duo’ and together controlling the homeostasis against depression, the liaison between them BDNF and 5-HT has been strengthened by pharmacological and stem cell based research." (PMID 19506722, 2008). "Social aversion (one of the depression related behaviour) in mice is mainly influenced by BDNF-regulated molecular pathways in the NAc and is counteracted by antidepressant drugs especially fluoxetine." (PMID 19506722, 2008). "It has been shown that BDNF expression and/or function is impaired in major depression or following stress paradigms, while it is up-regulated by physical exercise and antidepressants." (PMID 18601743, 2008). "Chronic corticosterone in addition to the influence on the 5-HT system, has been shown to impair hippocampal BDNF function, which is comparable with the hippocampal atrophy reported in major depression." (PMID 19506722, 2008). "Preclinical and clinical studies have suggested dysregulation in BDNF occurs under conditions of chronic stress and depression." (PMID 17944926, 2007). "Several lines of evidence from human and animal studies implicate BDNF in the pathogenesis of stress-induced depression and the delayed efficacy of antidepressant drugs." (PMID 18301726, 2007). "Alterations in BDNF expression in specific neuron subpopulations contribute to various pathologies, including depression, epilepsy, and Alzheimer's, Huntington's, and Parkinson's diseases." (PMID 17149751, 2007). "Several lines of evidence implicate BDNF in the pathogenesis of stress-induced depression and the delayed efficacy of antidepressant drugs." (PMID 18301726, 2007). "An opposite effect was observed in the hippocampus, where CFA down-regulated NK-1 receptor and BDNF gene expression, phenomena previously observed in immobilization models of stress and depression." (PMID 17974009, 2007).